CHEK1 (checkpoint kinase 1)
Diseases named in the same sentence as CHEK1 in open-access papers (continued):
Sharing a sentence is not in itself a finding about the gene and the disease.
neuroblastoma (37 papers, 2007 to 2026). Neuroblastoma (NB) is the most common solid, extracranial childhood tumor. "Using an isogenic 11q deleted model system and high-throughput drug screening, we identify checkpoint kinase 1 (CHK1) as a potential therapeutic target for 11q deleted neuroblastoma." (PMID 36237330, 2022). "More recently, the DNA damage response protein (DDR) checkpoint kinase 1 (Chk1) has been identified as being overactive in neuroblastoma." (PMID 24349301, 2013). "A kinome screen with RNAi found that loss of checkpoint kinase 1 (CHK1) was cytotoxic with ≥50% growth inhibition in neuroblastoma cells but no inhibition in normal somatic cells." (PMID 26771642, 2016). "WEE1, CHEK1, BRCA1, FANCD2, PARP1, and phosphorylation of CHEK1 and ATR were significantly reduced in TRPM2 deleted neuroblastoma and myeloid leukemia cells after doxorubicin treatment." (PMID 35428820, 2022). "Interestingly, simultaneous pharmacologic inhibition of CHEK1 and WEE1, both miR-497 targets, acted synergistically to impair neuroblastoma cell growth in vitro and in vivo, further demonstrating the therapeutic potential of miR-497." (PMID 26824183, 2016).
Fanconi anemia (33 papers, 2009 to 2025). Fanconi anemia (FA) is a hereditary DNA repair disorder characterized by progressive pancytopenia with bone marrow failure, variable congenital malformations and predisposition to develop hematological or solid tumors. "Additionally, significant roles are played by PALB2, ATM, ATR, CHEK1, CHEK2, RAD51, and genes linked to Fanconi anaemia." (PMID 40069561, 2025). "We found that the knockdown of TAPIRs leads to the suppression of genes essential for the DNA-damage response, as there are BRCA1 (breast cancer 1, early-onset), CHEK1 (Checkpoint kinase 1), CLSPN (Claspin), and genes encoding proteins of the Fanconi anemia pathway." (PMID 32365858, 2020). "Considerable evidence is now available suggesting that loss of one or several key genes involved in HR, among these ATM, CHEK1/2, NBN, RAD51 and genes of the Fanconi Anemia complementation group, is associated with sensitivity of cancers to platinum drugs and PARP inhibitors." (PMID 27756336, 2016). "In addition to BRCA1/2 deficiency, the amplification of EMSY and deficiencies in PTEN, Fanconi Anemia genes, RAD genes and DNA repair genes involved in HR (including ATM, ATR and CHEK1/2) have also been identified to cause HR defects in human cancer." (PMID 25437005, 2014). "HRR alterations involve Fanconi anemia genes (PALB2, FANCA, FANCL, FANCI, FANCC), core RAD genes (RAD50, RAD51, RAD51B, RAD51C) as well as DNA damage response genes (ATM, ATR, CHEK1, CHEK2)." (PMID 36531003, 2022). "Again, DNA repair and cell-cycle-related genes (e.g., Fanca, Brca1, Eme1, Cdc6, Cdc7, Chek1) are enriched (e.g., KEGG terms: Fanconi anemia pathway, homologous recombination, cell cycle, Base excision repair)." (PMID 28638111, 2017).
cervical carcinoma (32 papers, 2009 to 2025). A carcinoma arising from either the exocervical squamous epithelium or the endocervical glandular epithelium. "CHEK1 and p-CHEK1 contribute to the development of cervical cancer." (PMID 32655987, 2020). "Among them, PLK1, ATM, CDK5 and CHEK1 are abnormally expressed in cervical cancer." (PMID 32655987, 2020). "In addition, COR promotes cancer cycle arrest at the G2/M phase via the checkpoint kinase 1 (CHK1)/cylinB1-cdc2 complex pathway in the cervical cancer cell line (HeLa) in vitro." (PMID 31207985, 2019). "This microRNA acts as a tumor suppressor in cervical cancer, by down-regulation of CHK1 (checkpoint kinase 1) gene and up-regulation of aprataxin, which leads to radiosensitivity." (PMID 32318335, 2020). "The same was found when the DNA repair candidate genes from cervical carcinoma (MSH5, OGG1) and lung squamous cell carcinoma (CHEK1) were analyzed." (PMID 27683114, 2016). "Moreover, downregulation of miR-424 contributes to the progression of cervical cancer via upregulation of target CHEK1 gene expression and phosphorylation of CHK1 protein, while its overexpression inhibits CHK1 expression." (PMID 34072593, 2021).
osteosarcoma (29 papers, 2013 to 2025). A usually aggressive malignant bone-forming mesenchymal neoplasm, predominantly affecting adolescents and young adults. "Overexpression of APOBEC3s was shown to increase responsiveness to targeted ATR (Ataxia Telangiectasia and Rad3-Related) and Chk1/2 (Checkpoint Kinase 1 and 2) inhibitors in acute myeloid leukemia and osteosarcoma cell lines." (PMID 41373684, 2025). "The Westernblot results further confirmed that palmatine reduces RRM2 expressionin both osteosarcoma cells and HVECs and decreases the expressionof cell cycle and DNA damage repair-related proteins, such as cyclinB1, cyclin E1, and CHEK1." (PMID 40834268, 2025). "In osteosarcoma, LB-100 and cisplatin treatments resulted in decreased ATM/ATR-mediated DNA damage response, leading to hyperphosphorylation of checkpoint kinase 1 (Chk1) and Chk2, and subsequently causing an increase of cyclin activity in these cells." (PMID 38184584, 2024). "Commercial carriers such as RNAiFectTM reagent (Qiagen), LipofectamineTM 2000 and OligofectamineTM(Invitrogen) were used to deliver CDC20, RAD51, and CHEK1 siRNA, respectively, and these studies were conducted in pancreatic, non-small-cell lung carcinoma (NSCLC), and osteosarcoma cell-lines." (PMID 25763370, 2015).
small cell lung carcinoma (28 papers, 2017 to 2025). Small cell lung cancer (SCLC) is a highly aggressive malignant neoplasm, accounting for 10-15% of lung cancer cases, characterized byrapid growth, and early metastasis. "CHEK1 inhibition can augment CD8 + T cells infiltration in vivo models of multiple immunocompetent small cell lung cancer." (PMID 36175893, 2022). "Similarly, pharmacological inhibition of polyadenosine diphosphate-ribose polymerase (PARP) and checkpoint kinase 1 (CHK1) in small-cell lung cancer results in the inhibition of the DDR pathway and activates the cGAS-STING pathway, evoking an anti-tumour immune response." (PMID 37448962, 2023). "Conversely, targeted inhibition of Chk1 (checkpoint kinase 1, a critical effector kinase for ATR) induced PD-L1 expression in both human and murine small cell lung cancer cell lines." (PMID 34298632, 2021). "In small cell lung cancer, the STING pathway could be activated by Poly ADP-ribose polymerase (PARP) and Checkpoint kinase 1 (CHK1) inhibitors and promotes anti-tumor immunity." (PMID 35978045, 2022).
gastric cancer (25 papers, 2007 to 2025). A primary or metastatic malignant neoplasm involving the stomach. "It has also been reported that CHEK1 is associated with breast and gastric cancers and thus has important clinical and prognostic significance." (PMID 36714024, 2023). "Nevertheless, some exceptions have been reported, in which high CHEK1 expression could also be associated with better prognostic outcomes in colorectal and gastric cancers." (PMID 40344565, 2025). "We screened eight DDR-related genes (ZBTB7A, POLQ, CHEK1, NPDC1, RAMP1, AXIN2, SFRP2, and APOD) to establish a risk model, which can predict the prognosis of gastric cancer patients and guide the clinical implementation of immunotherapy." (PMID 36578802, 2022). "CHEK1 was used as the query and the result showed that the gene was overexpressed in brain, cervical, colorectal, and gastric cancers and also underexpressed in another brain cancer when compared to the normal counterpart." (PMID 32178478, 2020). "Although different studies have reported CHEK1 mutations in endometrial, colorectal, and stomach carcinomas with microsatellite instability, the potential role of the CHEK1 gene in the pathogenesis of human cancer is not well defined." (PMID 32178478, 2020). "However, some genes (CHEK1, CDKN1A, CDKN2A, CCNB1, etc.)from the B-terms of the close discovery were cell cycle regulators, suggesting that anandamide might be related to cell cycle in gastric cancer." (PMID 24949851, 2014).
lung adenocarcinoma (25 papers, 2015 to 2026). A carcinoma that arises from the lung and is characterized by the presence of malignant glandular epithelial cells. "Applied to lung adenocarcinoma (LUAD) scRNA-seq data, PICDGI recovered known oncogenes and tumor suppressors and nominated novel candidate drivers, including JPH1 and CHEK1, which are implicated in calcium signaling, mitochondrial regulation, and DNA repair." (PMID 42044093, 2026). "Particularly CHEK1, which encodes for the cell cycle checkpoint kinase CHK1, is significantly overexpressed in SCLC, compared to lung adenocarcinoma." (PMID 29138515, 2017). "For instance, a study screened and validated CHEK1 gene as significantly overexpressed in lung adenocarcinoma (LUAD) and lung squamous cell carcinoma (LUSC) by integrating multiple chip datasets from the GEO database, and its overexpression was significantly associated with poor patient prognosis." (PMID 41564103, 2026). "In addition, studies in lung adenocarcinoma (LAC) cells have shown that LINC00485 directly binds to miRNA-195 to up-regulate checkpoint kinase 1 (CHEK1) expression, contributing to LAC cell proliferation and cisplatin resistance." (PMID 33461166, 2021). "In addition, promoter methylation, amplification, and miRNA regulation in patients with lung adenocarcinoma may lead to the upregulation of the CHEK1 gene, which may be a marker for predicting the survival rate of patients with lung adenocarcinoma." (PMID 38783288, 2024). "Our study supports the use of checkpoint kinase 1 (CHK1) pharmacological inhibitors, in targeted MYBL2 High patient cohorts, as a future therapy to improve lung adenocarcinoma patient outcomes." (PMID 33489883, 2020).
acute myeloid leukemia (20 papers, 2007 to 2025). Acute myeloid leukemia (AML) is a group of neoplasms arising from precursor cells committed to the myeloid cell-line differentiation. "It is not clear how Fms-like tyrosine kinase 3-internal tandem duplications (FLT3-ITD) regulates checkpoint kinase 1 (CHK1) in acute myeloid leukemia (AML)." (PMID 34168220, 2021).
bladder cancer (20 papers, 2016 to 2026). "Knockdown of CHEK1 led to decreased cell viability and increased cisplatin sensitivity, and high CHEK1 mRNA expression was associated with poor prognosis in several tumors, including bladder cancer." (PMID 37588099, 2023). "For the biomarkers identified from the mRNA data, it has been discovered that patients with low expression of CHEK1 have a higher survival rate in bladder cancer than those with high expression of CHEK1." (PMID 38678587, 2024). "DNA damage which was observed through the interaction of 19-BJB with nucleotide chains and affected DNA repair resulted in the activation of checkpoint kinase 1 (Chk1) and checkpoint kinase 2 (Chk2) in bladder cancer cell lines." (PMID 33724994, 2021). "We therefore explored the efficacy of the combination of gemcitabine and AZD7762, a checkpoint kinase 1/2 (CHK1/2) inhibitor, for bladder cancer." (PMID 28049532, 2017).
multiple myeloma (17 papers, 2011 to 2026). "In multiple myeloma, high CHEK1 expression is associated with poor outcomes, promoting chromosomal instability and drug resistance." (PMID 41564103, 2026). "Samples from multiple myeloma (MM) patients exhibited significantly higher levels of Checkpoint Kinase 1 (CHEK1) expression than normal plasma cells, and elevated CHEK1 expression were linked to worse outcomes in MM patients." (PMID 39439468, 2024). "Previous evidence increased expression of Chek1-induced cell proliferation of multiple myeloma, leading to a poor prognosis." (PMID 35495761, 2022). "Multiple myeloma (MM) cells expressed CircCHEK1_246aa is mainly in the CHEK1 kinase catalytic centre, and mature circCHEK1_246aa can be secreted into the bone marrow microenvironment." (PMID 34996480, 2022). "In this region it interacts with native centrosomal protein 170 (CEP170) to attenuate mutant CEP170 expression in MM cells, promoting multiple myeloma (MM) by inducing chromosomal instability and bone lesion formation, exerting a similar function to full-length CHEK1." (PMID 34996480, 2022). "What is more, CHEK1 expression has implications in several non-neoplastic diseases, such as Alzheimer’s disease, multiple myeloma, autoimmune disease and so on." (PMID 40561071, 2025).
endometrial cancer (14 papers, 2015 to 2026). Primary or metastatic malignant neoplasm involving the endometrium (mucous membrane that lines the endometrial cavity). "Elevated CHEK1 protein levels were strongly associated with deep myometrial infiltration, suggesting CHEK1’s potential role in endometrial cancer pathophysiology." (PMID 41564103, 2026). "In endometrial cancer, reduced CHEK1 expression has been identified as a risk factor for disease recurrence and may serve as a stratification marker for patient prognosis and therapeutic decision‐making." (PMID 41235705, 2025). "In this study, we found significantly elevated mRNA expression levels of the oncoprotein KRAS, along with two replicative stress markers, ATR and CHEK1, in samples of endometrial carcinomas of endometrium (ECE) from patients with relapse." (PMID 38669256, 2024). "Increased expression of the KRAS oncogene is identified in 22–43% of endometrial carcinomas and leads to changes in the expression of ATR and CHEK1 genes, key components of the ATR-CHEK1-WEE1 signaling pathway responsible for DNA replication and repair." (PMID 38669256, 2024). "The mRNA expression levels of KRAS, ATR, CHEK1 genes in endometrial cancer tissue samples at stage I with and without recurrence in anamnesis." (PMID 38669256, 2024). "Checkpoint kinase 1 (CHK1S345), selectively inhibited by prexasertib (ACR-368), was exclusively quantified by RPPA and has demonstrated early promising results as a therapeutic target in platinum-resistant endometrial cancer (NCT05548296)." (PMID 38254014, 2024).
head and neck squamous cell carcinoma (14 papers, 2016 to 2025). A squamous cell carcinoma that arises from any of the following anatomic sites: lip and oral cavity, nasal cavity, paranasal sinuses, pharynx, larynx, and salivary glands. "Prexasertib, an inhibitor of CHK1/2 (checkpoint kinase 1/2), reduced NOTCH signaling and Skp2, enhanced the in vitro and in vivo response of head and neck squamous cell carcinoma to cisplatin and radiation, in line with another study that claimed that Skp2 is a downstream target of NOTCH signaling." (PMID 34068643, 2021).
medulloblastoma (13 papers, 2007 to 2022). A malignant, invasive embryonal neoplasm arising from the cerebellum. "As previously reported, CHEK1, both at the mRNA and protein levels, is highly expressed in medulloblastoma and T-cell acute lymphoblastic leukemia." (PMID 32596342, 2020). "Elevated CHEK1 expression in medulloblastoma is an adverse prognostic marker." (PMID 32596342, 2020).
viral infection (12 papers, 2014 to 2026). "Previous studies have revealed that ASFV could elicit the Ataxia Telangiectasia mutated and Rad3-related protein-Checkpoint kinase 1 (ATR-Chk1) pathway, which is required for successful viral infection of host cells." (PMID 33374251, 2020).
serous ovarian cancer (10 papers, 2015 to 2024). "Ovarian serous cancers, a major subtype, show dysregulated DNA repair pathway and often display a high level of CHEK1 (CHK1), a cell cycle regulator and DNA damage sensor." (PMID 25884494, 2015). "Checkpoint kinase 1 (Chk1) and epidermal growth factor receptor (EGFR) are therapeutic targets for treatment of acute and chronic leukemias and high-grade serous ovarian cancer." (PMID 34067242, 2021).
liver cancer (9 papers, 2019 to 2025). An epithelial or non-epithelial malignant neoplasm that arises from the liver. "Utilizing bioinformatics analysis of the GEO database, we identified differential expression of miR-424-5p and CHEK1 in liver cancer tissues." (PMID 39309825, 2024). "This discovery not only uncovers a potential regulatory link between miR-424-5p and CHEK1 but also suggests miR-424-5p as a promising molecular target for the development of new therapeutic strategies against liver cancer." (PMID 39309825, 2024). "Previous studies have established that miR-424-5p can suppress tumor biological behaviors in liver cancer, while CHEK1 promotes the proliferation, migration, and invasion of liver cancer cells." (PMID 39309825, 2024). "Intriguingly, CHEK1 expression in liver cancer cells appears to be under the dual regulation of miR-424-5p and miR-199-5p." (PMID 39309825, 2024). "However, in some cancers, including liver cancer, tumor cells have been observed to upregulate CHEK1." (PMID 39309825, 2024). "Specifically, it was previously unknown whether miR-424-5p could target CHEK1 to modulate its expression levels in liver cancer." (PMID 39309825, 2024).
sarcoma (9 papers, 2017 to 2026). A usually aggressive malignant neoplasm of the soft tissue or bone. "CHEK1 inhibition (e.g., prexasertib) abrogates S-phase checkpoint control and can precipitate replication catastrophe in RS-primed EwS cells, with robust preclinical activity and early clinical signals in translocation-driven sarcomas (CHEK1 targeting)." (PMID 41301081, 2025). "By analyzing data from TCGA sarcoma cohort, we further confirmeda strong positive correlation between RRM2 and cyclin B1, cyclin E1,and CHEK1 expression, as well as a negative correlation with TP53expression." (PMID 40834268, 2025).
ataxia telangiectasia (8 papers, 2014 to 2024). Ataxia-telangiectasia is the association of severe combined immunodeficiency (affecting mainly the humoral immune response) with progressive cerebellar ataxia. "Another report suggested that BRU and 8 Gy of gamma radiation induce Nrf2-dependent ataxia telangiectasia mutations and the Rad3-related kinase (ATR)-checkpoint kinase 1 (CHK1) pathway." (PMID 35368867, 2022).